FUNDC1 (FUN14 domain containing 1)
Diseases named in the same sentence as FUNDC1 in open-access papers (continued):
Sharing a sentence is not in itself a finding about the gene and the disease.
preeclampsia (2 papers, 2022 to 2024). Preeclampsia is a hypertensive disorder of pregnancy that is characterized by new-onset hypertension with proteinuria presenting after 20 weeks of gestation, and depending on mild or severe forms may initially present with severe headache, visual disturbances, and hyperreflexia. "Low levels of FUNDC1 ubiquitination have been found in hypoxic trophoblast cells and the placentas of pregnant women with preeclampsia." (PMID 38390447, 2024). "In this review, we compiled current studies investigating the role of BNIP3, DRAM1, and FUNDC1, mediators of receptor-mediated mitophagy, in the progression of preeclampsia and the role of mitophagy pathways in the pathophysiology of low birth weight." (PMID 36289801, 2022). "The decrease in FUNDC1 ubiquitination promotes autophagy, resulting in excessive enhancement of autophagy and destruction of normal mitochondria, which are related to the occurrence and development of preeclampsia." (PMID 38390447, 2024).
triple-negative breast carcinoma (2 papers, 2021 to 2022). An invasive breast carcinoma which is negative for expression of estrogen receptor (ER), progesterone receptor (PR), and human epidermal growth factor receptor 2 (HER2). "Furthermore, in a mouse xenograft model, melatonin inhibited triple-negative breast cancer progression through the Inc049808-FUN14 domain-containing 1 (FUNDC1) pathway." (PMID 35409137, 2022).
asthma (1 paper, 2025). "For instance, FUN14 domain-containing protein 1 (FUNDC1) dominates hypoxia-induced mitophagy in pulmonary fibrosis (PF), whereas BCL2/Adenovirus E1B 19 kDa protein-interacting protein 3 (BNIP3) is pivotal in asthma-related airway remodeling." (PMID 41026942, 2025).
bladder cancer (1 paper, 2019). "For bladder cancer, FUNDC1 was found to have a protective effect on overall survival (OS: HR = 0.59, 95% CI from 0.44 to 0.8, logrank P = 0.00045)." (PMID 31998650, 2019). "However, FUNDC1 worsened relapse-free survival in bladder cancer (RFS: HR = 2.15, 95% CI from 1.01 to 4.58, logrank P = 0.043)." (PMID 31998650, 2019).
childhood leukemia (1 paper, 2024). An acute or chronic leukemia that occurs during childhood. "However, the role of FUNDC1 in childhood leukemia (CL) remains unknown." (PMID 38947217, 2024).
chronic heart failure (1 paper, 2025). "In contrast, chronic heart failure (HF) involves MAM uncoupling due to reduced expression or dysfunction of tethering proteins such as mitofusin-2 (MFN2) and FUNDC1, impairing Ca2+ signaling, mitophagy, and bioenergetics." (PMID 41294815, 2025).
Cognitive impairment (1 paper, 2023). Abnormal cognition is characterized by deficits in thinking, reasoning, or remembering. "Resultantly, in vivo analysis revealed that NTRK1 knockdown induced mouse cognitive impairment and hippocampal tissue damage, in addition to inactivating the AMPK/ULK1/FUNDC1 pathway activity and mitophagy in the hippocampal tissues of mice." (PMID 37907480, 2023). "Mechanistically,NTRK1 knockdown might induce cognitive impairment and hippocampal neuron damage through the suppression of mitophagy via inactivating theAMPK/ULK1/FUNDC1 pathway." (PMID 37907480, 2023).
COVID-19 (1 paper, 2023). A disease caused by infection with severe acute respiratory syndrome coronavirus 2. "In the validation dataset, we found consistent metabolic trends in T cells; namely, we found that COVID-19 T cells downregulate key mitophagy genes FUNDC1, PINK1, and CSNK2B and upregulate key Rho GTPase genes RHOA, RHOBTB1, and ARAP3 as well as MTOR compared to HIV-1+ individuals." (PMID 36992700, 2023).
dilated cardiomyopathy (1 paper, 2022). Cardiomyopathy which is characterized by dilation and contractile dysfunction of the left and right ventricles. "Salient findings from our present study revealed that levels of FUNDC1 were significantly downregulated in heart tissues of patients with dilated cardiomyopathy (DCM), in heart tissues of mice with DOX insult, as well as in DOX-treated AC-16 cardiomyocytes." (PMID 36470869, 2022). "FUNDC1 was downregulated in heart tissues in patients with dilated cardiomyopathy (DCM) and DOX-challenged mice." (PMID 36470869, 2022). "Our data revealed the downregulation of FUNDC1 in heart tissues from patients with dilated cardiomyopathy (DCM) and mice with DOX challenge." (PMID 36470869, 2022).
endometrial carcinoma (1 paper, 2024). A malignant tumor arising from the epithelium that lines the cavity of the uterine body. "Gene set enrichment analysis (GSEA) analysis indicated that abnormal expression of FUNDC1 was involved in endometrial cancer, NOD-like receptor signaling pathway and cytokine signaling in the immune system." (PMID 39668821, 2024). "Gene set enrichment analysis (GSEA) indicated that abnormal expression of FUNDC1 was involved in endometrial cancer, NOD-like receptor signaling pathway and cytokine signaling in the immune system." (PMID 39668821, 2024).
Glucose intolerance (1 paper, 2025). Glucose intolerance (GI) can be defined as dysglycemia that comprises both prediabetes and diabetes. "Intriguingly, ablation of the mitophagy receptor FUNDC1 negated the beneficial effects of CK2α deletion on body weight, liver weight, WAT (epididymal and inguinal), and glucose intolerance under HFD challenge, while FUNDC1 deletion alone did not produce any significant effects." (PMID 40656543, 2025).
hyperhomocysteinemia (1 paper, 2023). A serious metabolic condition caused by mutations in the MTHFR gene, medications, or nutritional deficiency. "In the hyperhomocysteinemia rat model, the mitophagy‐related proteins FUN14 domain containing 1 and LC3B and the mitochondrial fusion proteins Mfn1 and Mfn2 are down‐regulated, whereas expression of the mitochondrial fission protein Drp1 is up‐regulated." (PMID 37208948, 2023).
Hyperinsulinemia (1 paper, 2025). An increased concentration of insulin in the blood. "FUNDC1 deletion alone did not significantly affect liver morphology, blood parameters, lipid droplet formation, or hyperinsulinemia under HFD conditions." (PMID 40656543, 2025).
ischemic disease (1 paper, 2022). Lack of blood supply to an area of the body, resulting in impairment of tissue oxygenation. "Studies have demonstrated that FUNDC1 is associated with the progression of ischemic disease, cancer, and metabolic disease." (PMID 35959490, 2022). "Instances of disease ranging from ischemic disease to cancer, as well as metabolic related disease, could also be influenced by FUNDC1." (PMID 35959490, 2022).
ischemic heart disease (1 paper, 2025). "The observation that mito-UPR activation can compensate for Fundc1 deficiency's effects highlights the mito-UPR's role in Fundc1-mediated cardioprotection and offers a basis for new ischemic heart disease therapies." (PMID 39744160, 2025).
kidney injuries (1 paper, 2021). "Specifically, we found that FUNDC1-mediated mitophagy is essential for EPO production in REPs during stress-induced kidney injuries and that damaged mitochondria accumulate in Fundc1-/- REPs as a result of impaired mitophagy." (PMID 33942716, 2021).
lentivirus infection (1 paper, 2024). Virus diseases caused by the Lentivirus genus. "The mRNA expression of Fundc1 was significantly reduced following shFundc1 lentivirus infection, with a mean decrease of approximately 50%." (PMID 39506876, 2024).
lung squamous cell carcinoma (1 paper, 2019). "Then, using the GEPIA and TIMER databases, we investigated the correlations between FUNDC1 expression and immune infiltration in cancers, especially liver hepatocellular carcinoma (LIHC), and lung squamous cell carcinoma (LUSC)." (PMID 31998650, 2019).
Myocardial fibrosis (1 paper, 2025). "Third, the mechanism underlying exercise-based CR remained unelucidated, particularly PINK1/Parkin or FUNDC1-dependent mitophagy, mitochondrial quality control, mitochondria-related oxidative stress, as well as their mechanisms of interaction in myocardial fibrosis." (PMID 40741139, 2025).
neuroblastoma (1 paper, 2023). Neuroblastoma (NB) is the most common solid, extracranial childhood tumor. "To investigate the role of FUNDC1 in TDP-43 degradation in neuron-like cells, we performed a longitudinal assessment of FUNDC1 overexpression in human SH-SY5Y neuroblastoma cells." (PMID 37951930, 2023).
periodontitis (1 paper, 2024). An acute or chronic inflammatory process that affects the tissues that surround and support the teeth. "The results pertaining to mitophagy-related markers indicated that the expression levels of mitophagy pathway-related genes (Bnip3 and Fundc1) and autophagy-related genes (Map1lc3a and Map1lc3b) were significantly upregulated in the periodontitis+TTM group when compared with the periodontitis group." (PMID 38892077, 2024).
proteinopathy (1 paper, 2023). "Here, our bioinformatical analyses reveal that mitophagy receptor gene FUNDC1 is co-expressed with TDP-43, and both TDP-43 and FUNDC1 expression is correlated with genes associated with mitochondrial protein import pathway in brain samples of patients diagnosed with TDP-43 proteinopathy." (PMID 37951930, 2023). "Together, our data support that FUNDC1 promotes the mitochondrial TDP-43 import by regulating proteins associated with the mitochondrial protein import pathway, and FUNDC1-mediated mitochondrial quality control plays an important role in TDP-43 homeostasis in TDP-43 proteinopathy." (PMID 37951930, 2023).
sarcopenia (1 paper, 2022). Progressive decline in muscle mass due to aging which results in decreased functional capacity of muscles. "In general, decreased levels of mitophagy markers such as PINK1, parkin BNIP3, NIX, PHB2, FUNDC1, and AMBRA1 are associated with a reduced quality of life in sarcopenia associated with aging." (PMID 36561214, 2022). "In addition, reduced levels of mitophagy markers such as PINK1, Parkin, BNIP3, NIX, PHB2, FUNDC1, and AMBRA1 negatively impact sarcopenia-related muscle weakness and the quality of life in the elderly." (PMID 36561214, 2022).
skin aging (1 paper, 2025). The gradual irreversible changes in structure of skin that occur as a result of the passage of time.. "This study systematically deciphers the multilayered mechanisms through which CJF extract antagonizes skin aging via the FUNDC1–mitophagy axis." (PMID 40867864, 2025).
skin cancer (1 paper, 2019). "In 8 datasets in PrognoScan, high FUNDC1 expression levels could be used as an independent risk factor for a poor prognosis in brain, breast, colorectal, and skin cancers." (PMID 31998650, 2019). "Notably, FUNDC1 expression was significantly correlated with a total of eight cancer types, including bladder, brain, breast, colorectal, head and neck, lung, ovarian, and skin cancers." (PMID 31998650, 2019).
steatosis (1 paper, 2025). Increased lipid within the cytoplasm of cells. "In vitro study using palmitic acid indicated an obligatory role for CK2α, FUNDC1 and ferroptosis in hepatocyte steatosis." (PMID 40656543, 2025).
thyroid cancer (1 paper, 2019). "Specifically, compared with a low expression level, a high expression level of FUNDC1 was correlated with a better OS in KIRC and LUSC and DFS in thyroid carcinoma (THCA)." (PMID 31998650, 2019).
type 2 diabetes (1 paper, 2022). "Our description of the regulatory mechanism involving FUNDC1-mediated mitophagy in models of type 2 diabetes offers new perspectives on the pathogenesis of DN." (PMID 35614934, 2022).
cancer (32 papers, 2017 to 2026). A tumor composed of atypical neoplastic, often pleomorphic cells that invade other tissues. "Dysregulation of mitophagy regulators, such as PINK1, Parkin, BNIP3, NIX, and FUNDC1, have been implicated in cancer progression." (PMID 41306556, 2025). "Next, we explored the potential relevance and underlying mechanisms of FUNDC1 expression in cancers." (PMID 31998650, 2019). "However, hypoxia, which represents a common hallmark of both CVDs and cancer, prevents FUNDC1 phosphorylation and thus enables LC3-II recognition and binding to FUNDC1, thereby targeting the mitochondria for mitophagy." (PMID 37726810, 2023). "The FUNDC1 has been implicated in mitochondrial reprogramming and cellular plasticity in cancer, with the help of mitochondrial matrix protease LonP that may potentially antagonize tumor growth." (PMID 35011599, 2021). "Receptor‐mediated mitophagy, which involves proteins such as FUNDC1, BBNIP3, and BNIP3L/NIX, is associated with treatment in cancer cells and prognosis." (PMID 38334464, 2024). "In early-stage cervical cancer, FUNDC1 expression is significantly higher in cancer cells compared to adjacent normal cells." (PMID 39763653, 2024). "FUN14 domain-containing 1 (FUNDC1) is a newly identified mitochondrial outer membrane protein and its dysregulation has been implicated in various human diseases, including cancers." (PMID 39472438, 2024). "This high FUNDC1 expression is negatively correlated with tumor progression and patient prognosis and can induce cancer cell apoptosis and increase sensitivity to cisplatin and ionizing radiation." (PMID 39763653, 2024). "Here, we discuss the roles that PINK1, Parkin, BNIP3, NIX, and FUNDC1 play in a wide array of cancers, clarifying the possible mechanisms of mitophagy in cancers." (PMID 36632220, 2023). "FUNDC1 is reported to play an important role in several diseases, such as cancer, cardiovascular disease, and neurological disorders, including AD." (PMID 37470054, 2023). "While inhibition of FUNDC1 resulted in increased sensitivity of cancer cells to the ionizing radiation and cisplatin." (PMID 36200262, 2022). "FUNDC1 is involved in the physiological and pathological processes of I/R injury, cancers, and metabolic-related diseases." (PMID 35959490, 2022). "As another hypoxia‐induced mitophagy receptor, FUNDC1 also plays critical roles in regulating the occurrence and progression of cancer." (PMID 36200262, 2022). "Nonetheless, future study is needed to examine such PANoptosis mechanism in the realm of cancer chemotherapy in various tumors, to offer guidance with regards to the impact of FUNDC1 on cancer therapy." (PMID 36470869, 2022). "The findings from this study indicate that FUNDC1 influences the prognosis of patients with cancers, probably via its interaction with infiltrating immune cells." (PMID 31998650, 2019). "Recent studies provide possible mechanisms explaining why FUNDC1 expression correlates with immune infiltration and different prognoses in pan-cancer." (PMID 31998650, 2019). "Taken together, these findings strongly suggest that FUNDC1 can serve as a prognostic biomarker in pan-cancer." (PMID 31998650, 2019). "Meanwhile, it is now clear that hypoxia, a common feature of cancers, can induce extensive mitochondrial degradation in a FUNDC1-dependent manner." (PMID 31998650, 2019). "This study explored the expression levels of FUNDC1 and visualized the prognostic landscape in pan-cancer using independent datasets in ONCOMINE and PROGNOSCAN and TCGA data in GEPIA and TIMER." (PMID 31998650, 2019). "The results indicated that FUNDC1 expression had significant correlations with tumor purity in 11 cancer types." (PMID 31998650, 2019). "Although FUNDC1 showed a protective effect on pan-cancer, a high expression level of FUNDC1 was detrimental to the survival of LIHC patients." (PMID 31998650, 2019).
cancer (continued). "In general, FUNDC1 was a favorable prognostic marker in cancers (OS: total number = 9,496, HR = 0.72, logrank P = 0; DFS: total number = 9,496, HR = 0.8, logrank P = 6.6E−09)." (PMID 31998650, 2019). "In GEPIA, we analyzed the role of FUNDC1 in each cancer type (number of cancer types = 33), as well as the overall effect of FUNDC1 on cancers." (PMID 31998650, 2019). "FUNDC1 mRNA expression levels were analyzed in Oncomine to examine FUNDC1 expression over a cancer-wide range." (PMID 31998650, 2019). "This study aimed to visualize the prognostic landscape of FUNDC1 in pan-cancer and investigate the relationship between FUNDC1 expression and immune infiltration." (PMID 31998650, 2019). "To further evaluate FUNDC1 expression in pan-cancer, we examined RNA sequencing data in TCGA using TIMER." (PMID 31998650, 2019). "FUNDC1-related mitochondrial dysfunction contributes to various pathophysiological processes, such as heart diseases, metabolic disorders, and cancers." (PMID 31998650, 2019). "Another major finding from this study is that FUNDC1 expression correlates with diverse immune infiltration levels in cancers, especially in LIHC and LUSC." (PMID 31998650, 2019). "For example, FUNDC1 can promote tumor progression and predict poor prognosis in some cancer types; however, it can also suppress carcinogenesis through mitophagy." (PMID 31998650, 2019). "In this study, we visualized the prognostic landscape of FUNDC1 in pan-cancer using databases, including ONCOMINE, PrognoScan, GEPIA, and Kaplan-Meier Plotter." (PMID 31998650, 2019). "Our study also provided evidence that the immune infiltration levels of antigen presenting cells (B cells and macrophages) are significantly correlated with the FUNDC1 expression level in cancers." (PMID 31998650, 2019). "These discrepant FUNDC1 expression levels in cancers across different databases are the result of heterogeneous data collection approaches, as well as underlying mechanisms with distinct biological properties." (PMID 31998650, 2019). "In PrognoScan, we explored the relationships between FUNDC1 expression and the prognosis of each cancer." (PMID 31998650, 2019). "Moreover, targeting FUNDC1 with X-rays can enhance mitochondrial autophagy for targeted cancer therapy." (PMID 39763653, 2024). "Interestingly, the classical PINK1‐Parkin pathway and mitophagy mediated by BNIP3/Nix and FUNDC1 in response to hypoxia are also involved in glycolytic metabolism in cancer cells." (PMID 36200262, 2022). "Overexpression of FUNDC1 is adequate for mitophagy of a number of cancer cell lines." (PMID 34699308, 2022). "In addition, Lon interaction with FUN14 domain-containing protein 1 (FUNDC1) protects cancer cells from ROS accumulation through stabilizing ETC Complex II and Complex V." (PMID 36154922, 2022). "The positive correlation between FUNDC1 expression and tumour progression can be attributed to hypoxia, but different degrees of mitophagy in different cancer contexts as well as the complex cancer microenvironment should also be responsible for the diverse effects." (PMID 36200262, 2022). "Globally, the effect of FUNDC1 on cancer cells depends on the cancer type." (PMID 36200262, 2022). "It has been reported that mitophagy can improve cancer cell survival by regulating apoptosis or improving the overall function of mitochondria, and FUNDC1 can also increase vascular endothelial growth factor (VEGF) receptor production and improve the nutrient supply of tumour cells." (PMID 36200262, 2022). "Thus, FUNDC1 was shown to enhance the progression of cancer and represented a poor prognosis in some tumors." (PMID 35011599, 2021). "Although, a positive correlation between FUNDC1 expression and tumor progression can be assumed as hypoxia, a microenvironmental characteristic of cancers, might induce FUNDC1-dependent mitophagy." (PMID 35011599, 2021). "In summary, FUNDC1 can affect pan-cancer prognosis and correlate with immune infiltration." (PMID 31998650, 2019).